PSD3 (pleckstrin and Sec7 domain containing 3)
Description:
Guanine nucleotide exchange factor for ARF6.
Synonyms: EFA6D; EFA6R; HCA67; KIAA0942; DKFZp761K1423
Tractability: Antibody: UniProt places it where antibodies can reach, with medium confidence; its Gene Ontology location is reachable by antibodies, with medium confidence. PROTAC: ubiquitination databases record sites on it; its protein half-life has been measured.
Gene: Protein-coding gene on chromosome 8 (18,527,303 to 19,084,730, reverse strand). Ensembl gene ENSG00000156011.
Subcellular location: Cell membrane; Cell projection, ruffle membrane; Postsynaptic density
Subcellular location (Human Protein Atlas): Nucleoplasm; Vesicles; Calyx; Cytosol; End piece; Mid piece; Principal piece
Gene Ontology:
Molecular function: guanyl-nucleotide exchange factor activity
Biological process: regulation of ARF protein signal transduction
Cellular component: ruffle membrane; plasma membrane; postsynaptic density
Genetic constraint (gnomAD): Loss-of-function variants: 41 observed, 93.14 expected, observed/expected ratio (o/e) 0.44, 90% interval 0.34 to 0.57. The upper end of that interval is the gene's LOEUF score, 0.57, which puts it in group 2 of 6, group 1 being the genes least tolerant of losing a copy. Missense variants: 1,484 observed, 1,250.8 expected, observed/expected ratio (o/e) 1.19, 90% interval 1.14 to 1.24. Synonymous variants: 533 observed, 461.76 expected, observed/expected ratio (o/e) 1.15, 90% interval 1.07 to 1.24.
Gene-disease validity (ClinGen):
ClinGen rates the evidence that PSD3 causes each of these diseases.
antecubital pterygium syndrome (autosomal dominant): Limited.
Homologues: Orthologues: macaque PSD3 (96% identical), chimpanzee PSD3 (96% identical), guinea pig PSD3 (85% identical), dog PSD3 (83% identical), mouse Psd3 (80% identical), rat Psd3 (79% identical), rabbit PSD3 (75% identical), pig PSD3 (73% identical), zebrafish psd3l (44% identical), tropical clawed frog psd3 (27% identical), Drosophila melanogaster siz (12% identical), Drosophila melanogaster garz (11% identical), and 4 more. Paralogues in human: PSD2 (34% identical), PSD (34% identical), PSD4 (26% identical), IQSEC1 (15% identical), MON2 (14% identical), IQSEC2 (14% identical), GBF1 (13% identical), IQSEC3 (13% identical), ARFGEF1 (12% identical), ARFGEF2 (12% identical), CYTH3 (10% identical), CYTH1 (10% identical), and 3 more.
Diseases named in the same sentence as PSD3 in open-access papers:
PSD3 is named in the same sentence as 43 diseases in open-access papers, as found by Europe PMC text mining. Sharing a sentence is not in itself a finding about the gene and the disease. The quoted sentences say what the papers report.
breast carcinoma (6 papers, 2020 to 2024). "PH and SEC7 domain-containing protein 3 variant PSD3:18 found downregulated in the AKT1 silenced sample compared to control was reported downregulated in breast cancer." (PMID 35892586, 2022). "In previous reports, the expression of PSD3 was shown to be associated with some cancers such as acute myeloid leukemia, breast cancer metastasis, and astrocytoma 17-19." (PMID 34405004, 2021). "PSD3 is considered to be a candidate metastasis suppressor gene, and its low expression has been observed to be associated with poor prognosis in ovarian cancer and metastasis in breast cancer." (PMID 34222474, 2021). "PSD3 acted as a potential biomarker predicting relapse of acute myeloid leukemia in cytogenetically normal adult patients and involved in breast cancer metastasis, astrocytoma and papillary thyroid cancer progression." (PMID 38287071, 2024). "Pleckstrin and sec7 domain-containing 3 (PSD3), also known as EFA6R, was shown to be associated with some cancers such as acute myeloid leukemia, breast cancer metastasis, and astrocytoma." (PMID 34405004, 2021). "In recent years, various human Pleckstrin and sec7 domain-containing 3 (PSD3) have been believed to be related to some tumors, like acute myeloid leukemia, breast cancer metastasis, astrocytoma progression." (PMID 36276977, 2022). "Likewise, in chromosome 8, arm-level gains of 8q and losses of 8p in human breast cancer SCNAs were further segmented into three amplification peaks involving STK3, MYC, and PTK2 and three deletion peaks involving CSMD1, PSD3, and IDO1 in hg19-aligned CMT SCNAs, respectively." (PMID 32680987, 2020).
papillary thyroid cancer (6 papers, 2021 to 2025). "Another PSD3-derived circRNA was found to be significantly upregulated in papillary thyroid cancer tissues and cell lines and was positively associated with a larger tumor size, TNM stage, and lymph node metastasis." (PMID 37884951, 2023). "For example, circ-PSD3 in tissue samples may be a potential diagnostic biomarker or molecular therapy target for papillary thyroid carcinoma." (PMID 34764979, 2021). "PSD3 inhibits apoptosis in papillary thyroid cancer by promoting proliferation, migration, invasion and G1/S transition." (PMID 36276977, 2022). "It was demonstrated that PSD3 was an oncogene that promoted proliferation, migration, invasion, and G1/S transition, while inhibited apoptotic in papillary thyroid cancer." (PMID 34405004, 2021).
Stroke (5 papers, 2015 to 2025). Sudden impairment of blood flow to a part of the brain due to occlusion or rupture of an artery to the brain. "In the current study, we focused on post-stroke day 3 and 7 (PSD3, 7), as numerous reports indicate that neuroinflammation and M1-like microglial polarization reach a peak between PSD3 and PSD7, before shifting toward reparative phenotypes." (PMID 41388741, 2025). "All mice were tested in the foot-fault task prior to stroke to establish baseline behavior, and again on PSD3 prior to cell transplantation." (PMID 33994947, 2021). "In an attempt to separate the neuroprotective effects of IL-1α from its neuroreparative effects, in these experiments we delayed IL-1α administration until PSD3, a time point at which the ischemic infarct is maximally evolved in our stroke model." (PMID 31727174, 2019). "Post-stroke treatment with a shh pathway agonist at psd3 after MCAo surgery thus supports that activation of the shh signaling pathway improves the behavioral outcome 7 days after ischemia onset." (PMID 25927436, 2015). "Stroke+vehicle mice continued to display significant increases in the percent slippage up to PSD21 relative to their own baseline (4.01 ± 0.62, 3.22 ± 0.52, 2.55 ± 0.35 percent slippage on PSD3, 8 and 21, respectively; PSD3, p < 0.0001; PSD8, p = 0.0001; PSD21, p = 0.03)." (PMID 38339065, 2024).
astrocytoma (3 papers, 2021 to 2024). "PSD3 also was discovered that was related to astrocytoma progression." (PMID 34405004, 2021).
thyroid cancer (3 papers, 2021 to 2025). "PSD3 (pleckstrin and sec7 domain-containing 3) is an oncogene highly expressed in thyroid cancer (TC), generating multiple circRNAs from distinct exons." (PMID 40925894, 2025). "The present investigation was designed to discover the relation between PSD3 and clinical characteristics, and explore the function of PSD3 in thyroid cancer by small interfering RNA (si-RNA)." (PMID 34405004, 2021). "To further explore the expression of PSD3 in thyroid cancer, we performed RNA sequencing on 40 pairs of PTC tissues and matched normal tissues, and obtained the same trend." (PMID 34405004, 2021). "In a word, PSD3 acted as an oncogene that promoted thyroid carcinoma progression and metastasis in PTC." (PMID 34405004, 2021). "But it was unknown that whether PSD3 took effect and how did it work in thyroid cancer." (PMID 34405004, 2021). "But it was not known whether PSD3 takes effect and how does it work in thyroid cancer." (PMID 34405004, 2021).
fatty liver disease (2 papers, 2022). A reversible condition wherein large vacuoles of triglyceride fat accumulate in liver cells via the process of steatosis. "We found that the PSD3 minor allele was associated with a lower prevalence of liver steatosis (P = 0.024), fibrosis (P = 0.049) and ballooning (P = 0.047), and with less severe fibrosis and ballooning (P = 0.040 and P = 0.048, respectively)." (PMID 35102341, 2022). "A mutation of leucine 186 to threonine in Pleckstrin and sec7 domain-containing 3 (PSD3) has been reported reducing the risk of fatty liver." (PMID 36569303, 2022). "Consistent with the human genetic data, downregulation of Psd3 resulted in protection against liver steatosis, inflammation and collagen deposition in these mice." (PMID 35102341, 2022). "Functional studies in vitro and in vivo demonstrate that targeting PSD3 protects against fatty liver disease." (PMID 35102341, 2022). "Moreover, Psd3 ASO treatment reduced the severity of liver steatosis." (PMID 35102341, 2022). "As predicted, Psd3-ASO downregulates the expression of PSD3 in mice induced by a NASH diet, and decreases the expression of the lipogenic enzymes acetyl-CoA carboxylase (ACC), fatty acid synthase (FAS), and stearoyl-CoA desaturase 1 (SCD1), which consequently alleviates hepatic steatosis." (PMID 36569303, 2022).
Hepatic fibrosis (2 papers, 2022 to 2023). The presence of excessive fibrous connective tissue in the liver. "The pathological functions of different PSD3-derived circRNAs have also been investigated in hepatic fibrosis and hepatitis C virus (HCV) infection." (PMID 37884951, 2023).
hepatocellular carcinoma (2 papers, 2022). A malignant tumor that arises from hepatocytes. "To confirm our data, we measured the intracellular lipid accumulation and triglyceride synthesis using radiolabelled tracers in human hepatoma cells (Huh7 cells) homozygous for the PSD3 186L allele, and obtained virtually identical results as McA-RH7777 cells." (PMID 35102341, 2022). "PSD3 is a protein-coding gene associated with hepatocellular carcinoma (HCC), one of the most common types of primary liver cancer that often occurs in people with chronic liver diseases." (PMID 35884374, 2022). "PSD3 downregulation by short interfering RNA reduces intracellular lipid content in primary human hepatocytes cultured in two and three dimensions, and in human and rodent hepatoma cells." (PMID 35102341, 2022). "In summary, PSD3 rs71519934 was associated with protection against FLD in individuals at risk and PSD3/Psd3 downregulation led to a reduction in hepatocellular fat content in human primary hepatocytes and in human and rodent hepatoma cells." (PMID 35102341, 2022).
hypertrophic cardiomyopathy (2 papers, 2023 to 2024). A condition in which the myocardium is hypertrophied without an obvious cause. "As for hypertrophic cardiomyopathy, PSD3 (Pleckstrin And Sec7 Domain Containing 3, 614440), as a pathogenic gene for Idiopathic Peripheral Autonomic Neuropathy, has also been reported to be differentially expressed across different CHD subtypes, validating our prediction." (PMID 39202774, 2024).
alcoholism (1 paper, 2015). "Of these 6 genes, LPAR1, PSD3, and GNAS are associated with brain-related phenotypes (alcoholism, memory, and brain waves), and LPAR1, PSD3, GNAS, and SRPK2 with eQTLs annotated in GTex or PheGenI in any human tissue (brain regions are not well represented in GTEx)." (PMID 26597164, 2015).
Alzheimer disease (1 paper, 2023). A progressive, neurodegenerative disease characterized by loss of function and death of nerve cells in several areas of the brain leading to loss of cognitive function such as memory and language. "At least in humans, PSD3 localization is restricted to the PFC, and PSD3 has been identified among candidate genes related to Alzheimer’s disease pathophysiology." (PMID 36830826, 2023).
Cirrhosis (1 paper, 2025). A chronic disorder of the liver in which liver tissue becomes scarred and is partially replaced by regenerative nodules and fibrotic tissue resulting in loss of liver function. "In our study, the methylation level of cg13674437/ADAM12 (a disintegrin and metalloproteinase) was lower, and cg06758847/PSD3 (Pleckstrin and Sec7 Domain Containing), and cg24595678/PSD3 were higher in cirrhosis patients who subsequently developed HCC than those who remained cancer-free." (PMID 39858049, 2025).
congenital heart disease (1 paper, 2024). A heart disease that is present at birth. "Similarly, PSD3 (Pleckstrin And Sec7 Domain Containing 3) has been shown to have specific copy number variants for CHD subtypes, including neo/HF-hypoplastic left heart syndrome, validating the specific role of genetic variants on congenital heart disease subtyping." (PMID 39202774, 2024).
dependence (1 paper, 2023). "Variants in the human PSD3 ortholog are associated with the alcohol drinking frequency and dependence." (PMID 37446084, 2023).
epilepsy (1 paper, 2024). A brain disorder characterized by episodes of abnormally increased neuronal discharge resulting in transient episodes of sensory or motor neurological dysfunction, or psychic dysfunction. "Based on the literature and database searches, there is association with seizures or epilepsy for five of the brain expressed genes (Marchf1, Tma16, Npy1r, Npy5r, Psd3)." (PMID 38862622, 2024). "Presently, Psd3 is the only gene in the interval with evidence of strain-dependent differences and a biological association with seizures or epilepsy." (PMID 38862622, 2024).
esophageal squamous cell carcinoma (1 paper, 2025). Esophageal squamous cell carcinoma (ESCC) is a type of esophageal carcinoma (EC) that can affect any part of the esophagus, but is usually located in the upper or middle third. "In this study, we selected PSD3, CD274, and TNFSF18 for integrated analysis based on a combination of transcriptomic screening, immunological relevance, and prognostic associations in esophageal squamous cell carcinoma (ESCC)." (PMID 40895529, 2025). "In summary, our study identifies PSD3 as a novel, context-dependent immuno-oncogenic factor in esophageal squamous cell carcinoma (ESCC)." (PMID 40895529, 2025). "In this study, we investigated PSD3, CD274 (PD-L1), and TNFSF18 as potential immune-related biomarkers in esophageal squamous cell carcinoma (ESCC) using integrative transcriptomic and experimental approaches." (PMID 40895529, 2025).
hypoplastic left heart syndrome (1 paper, 2024). Hypoplastic left heart syndrome (HLHS) refers to the abnormal development of the left-sided cardiac structures, resulting in obstruction to blood flow from the left ventricular outflow tract. "PSD3 (Pleckstrin And Sec7 Domain Containing 3, 614440) has been shown to contain specific functional copy number variants at the genomic level during the pathogenesis of Neo/HF-hypoplastic left heart syndrome." (PMID 39202774, 2024).
liver disease (1 paper, 2022). "Considering these results, we further tested the association between the PSD3 variant and the protection against liver disease in an independent replication cohort of obese (BMI ≥ 30 kg m−2) central European participants at risk for liver disease." (PMID 35102341, 2022).
lymph node metastasis (1 paper, 2021). "In the cohort of TCGA, we discovered that higher PSD3 expression was associated with a higher occurrence rate of classical histological type (P=0.009) and a higher risk of lymph node metastasis (P=0.016)." (PMID 34405004, 2021). "Also, the clinical analyses indicated that higher PSD3 expression increased the risk of lymph node metastasis and the incidence rate of classical histological type in PTC patients by logistic regression in the TCGA cohort." (PMID 34405004, 2021). "Multivariate logistic regression also ulteriorly demonstrated that PSD3 expression (P=0.028), primary neoplasm focus type (P=0.004), lymph node metastasis (P<0.001), and metastasis (P=0.02) were associated with the incidence rate of classical histological type." (PMID 34405004, 2021). "Univariate logistic regression confirmed that higher PSD3 expression (P=0.024), primary neoplasm focus type (P=0.007), lymph node metastasis (P<0.001), distant metastasis (P=0.035), and status (P=0.037) were associated with an incidence rate of classical histological type." (PMID 34405004, 2021). "But in the validated cohort, the PSD3 expression was connected with age and disease stage, rather than histological type and lymph node metastasis." (PMID 34405004, 2021).
non-alcoholic steatohepatitis (1 paper, 2022). "Consistent with this, Psd3 downregulation by antisense oligonucleotides in vivo protects against FLD in mice fed a non-alcoholic steatohepatitis-inducing diet." (PMID 35102341, 2022). "Mice were fed a non-alcoholic steatohepatitis (NASH)-inducing diet for a total of 50 weeks, and during the last 16 weeks, groups of mice were treated with Psd3 ASO, control ASO or saline." (PMID 35102341, 2022).
squamous cell lung carcinoma (1 paper, 2014). A carcinoma arising from squamous bronchial epithelial cells. "In this case, a partial KTN1 pseudogene inserted into the last intron of PSD3 in a primary squamous cell lung cancer." (PMID 24714652, 2014).
steatosis (1 paper, 2022). Increased lipid within the cytoplasm of cells. "Interestingly however, the sample from one heterozygous patient characterized by the lowest grade of steatosis also showed the weakest staining intensity for PSD3." (PMID 35102341, 2022).
thyroid (1 paper, 2021). "Then, we analyzed the level of PSD3 expression in thyroid malignancy and the connection with clinical manifestation in The Cancer Genome Atlas (TCGA)." (PMID 34405004, 2021).
cancer (10 papers, 2015 to 2025). A tumor composed of atypical neoplastic, often pleomorphic cells that invade other tissues. "Given the immunomodulatory roles of CD274 and TNFSF18, along with the emerging relevance of PSD3 in cancer biology, we next investigated their associations with tumor-infiltrating immune cells using immune deconvolution data from the GEO dataset GEO dataset." (PMID 40895529, 2025). "In particular, the PSD3 gene has been shown to be associated with cancer prognosis or therapeutic outcomes." (PMID 33628643, 2021). "PSD3, though less well-characterized in the context of cancer, has been associated with intracellular signaling and may contribute to oncogenic processes through modulation of the cytoskeleton or vesicle trafficking." (PMID 40895529, 2025). "In recent years, variants of the human PSD3 were shown to be associated with some cancers." (PMID 34405004, 2021). "This interval spans a single gene–Psd3–that has been associated with immune disease and cancer." (PMID 34794440, 2021). "PSD3 emerged from our pan-cancer expression and co-expression analyses as a novel and previously uncharacterized gene in ESCC, showing strong associations with immune-related pathways and clinical outcomes." (PMID 40895529, 2025). "Lastly, while CD274 and TNFSF18 are well-characterized in immune signaling, PSD3’s role in cancer remains poorly defined and should be interpreted with caution." (PMID 40895529, 2025). "Given these multifaceted roles, PSD3 emerges as a particularly attractive candidate for further investigation in the context of both tumor biology and cancer immunotherapy." (PMID 40895529, 2025). "PSD3 (Pleckstrin and Sec7 Domain Containing 3), by contrast, has received limited attention in cancer research." (PMID 40895529, 2025). "Circ-PSD3 limits the replicative potential of cancer cells and impedes apoptosis by regulating HEMGN." (PMID 36230649, 2022). "PSD3 (encoding Pleckstrin and SEC7 domains-containing protein 3) is a cancer risk gene that has been associated with memory functions (rs901732, intronic, p = 3.7e-8; rs1386687, intronic, p = 7.9e-6; Framingham Heart Study)." (PMID 26597164, 2015). "The circRNAs produced by PSD3 pre-mRNA have attracted attention in cancer and other diseases." (PMID 37884951, 2023). "Additionally, both the proximal and the distal gene to the SNP, NAT2 and PSD3, respectively, are strongly correlated with both cancer and T2D." (PMID 35884374, 2022). "To establish a foundational understanding of PSD3, CD274 (PD-L1), and TNFSF18 expression in cancer, we first conducted a comparative analysis of their mRNA levels across a wide array of tumor types using The Cancer Genome Atlas (TCGA) datasets." (PMID 40895529, 2025).